SFRP1 (secreted frizzled related protein 1)
Diseases named in the same sentence as SFRP1 in open-access papers (continued):
Sharing a sentence is not in itself a finding about the gene and the disease.
ductal carcinoma in situ (2 papers, 2020 to 2023). "We propose these three genes (FGF2, GAS1, and SFRP1) as potential biomarkers of ductal carcinoma in situ progression, suggesting that their downregulation may be involved in the transition of stationary to migrating invasive epithelial cells." (PMID 32050925, 2020). "A very low expression of SFRP1 was detected in the MCF10DCIS cell line, which mimics a ductal carcinoma in situ." (PMID 37190179, 2023). "Comparing pure ductal carcinoma in situ and in-situ component six differentially expressed genes were found, three of them (FGF2, GAS1, and SFRP1), play a role in cell invasiveness." (PMID 32050925, 2020). "The increase in SFRP1 expression in ductal carcinoma in situ in the MCF10DCIS cell line modified neither cell viability nor spheroid growth, regardless of the culture condition." (PMID 37190179, 2023). "However, we observed that SFRP1 overexpression in MCF10DCIS increased ESR1 expression, and then increased cell migration abilities in E2 conditions, while it decreased this expression in EtOH condition, suggesting that the role of SFRP1 in ERα-negative ductal carcinoma in situ could be E2-dependent." (PMID 37190179, 2023).
dyslipidemia (2 papers, 2013 to 2016). "Additional research must be undertaken to investigate the relationship between Sfrp1 loss and metabolic syndromes." (PMID 24339864, 2013).
embryonal carcinoma (2 papers, 2010 to 2014). A non-seminomatous malignant germ cell tumor characterized by the presence of large germ cells with abundant cytoplasm resembling epithelial cells, geographic necrosis, high mitotic activity, and pseudoglandular and pseudopapillary structures formation. "The inhibition of WNT transcription and activation of NOTCH are features of undifferentiated human embryonal carcinoma and ES cells, and may be mediated by the SFRP1 gene, which is repressed in differentiating NT2/D1 cells (derived from human EC cells) after treatment with retinoic acid." (PMID 24738045, 2014).
endometriosis (2 papers, 2024 to 2026). The growth of functional endometrial tissue in anatomic sites outside the uterine body. "In hESC cells co-cultured with gestational epithelial endometriosis organoids, SFRP1, CDC42, RAC1, and WASF3 were upregulated, while PTK2B was downregulated, reflecting the miRNA cargo of ENDO-GEST-derived EVs." (PMID 42282918, 2026). "Additionally, GRIK1-AS1 can impede DNMT1 from binding to the SRFP1 promoter, resulting in SFRP1 hypomethylation and subsequent upregulation, thereby accelerating the progression of endometriosis." (PMID 38408075, 2024).
fibrosarcoma (2 papers, 2007 to 2019). A malignant mesenchymal fibroblastic neoplasm affecting the soft tissue and bone. "The ECM gene cluster including the Lum, Sfrp1, Fbln5, Chad, Kera, Aspn, and Omd genes was found to be distinctly more activated in granulomas than in fibrosarcomas." (PMID 30621584, 2019).
fibrosis (2 papers, 2013 to 2023). the formation of excess fibrous connective tissue in an organ or tissue in a reparative or reactive process. "Cluster 10 (fibroblast-Wif1) showed increased expression of genes (Wif1, Dkk3, Sfrp1, Sfrp2) involved in negative regulation of Wnt signaling pathway, which has been considered to inhibit cardiac fibrosis." (PMID 36805782, 2023). "Of 3016 SNPs evaluated, eight were significantly associated with fibrosis risk (e.g., SFRP2 rs11937424: OR = 2.19, 95% CI 1.48-3.23, P = 0.00004), and seven were significantly associated with inflammation risk (e.g., SFRP1 rs16890282: OR = 2.15, 95% CI 1.39-3.16, P = 0.0004)." (PMID 24386373, 2013).
Hepatic steatosis (2 papers, 2013 to 2023). Steatosis is a term used to denote lipid accumulation within hepatocytes. "Although we did not observe any significant differences in gross liver weight, we did observe increased liver steatosis in Sfrp1-/- mice fed a HFD." (PMID 24339864, 2013). "For example, mice deficient in Sfrp1 exhibit increased adiposity and hepatic steatosis, and SFRP5 signaling has been shown to suppress non-alcoholic steatohepatitis." (PMID 38137817, 2023). "Interestingly, some genes that have been described to suppress the high body fat phenotype, hepatic steatosis, and potentially also myosteatosis are strongly downregulated in tumors because they are putative tumor-suppressor genes, such as SFRP1, SFRP5, and DKK3." (PMID 38137817, 2023). "Our data reveal that Sfrp1-/- mice exhibit increased adipocity in WAT, hepatic steatosis, glucose homeostasis irregularities and increased inflammatory repsonses." (PMID 24339864, 2013).
infarction (2 papers, 2017 to 2025). A localised pathological necrosis of tissue resulting from obstruction of the blood supply usually by a thrombus, an embolus, or vascular torsion. "It has been demonstrated that sFRP1 is related to maturation in cardiomyocytes, proangiogenic effects, endothelial cells movement, and the post-infarction scar size." (PMID 28947991, 2017). "SFRP1 protects rat cardiomyoblasts from hypoxia/re-oxygenation injury, myocardial damage, early leukocyte infiltration, and apoptosis, and it increases capillary density and improves myocardial function after infarction." (PMID 40921935, 2025).
Insulin resistance (2 papers, 2020 to 2023). Increased resistance towards insulin, that is, diminished effectiveness of insulin in reducing blood glucose levels. "Obese subjects with insulin resistance (higher HOMA-IR and lower oral glucose insulin sensitivity index) had higher expressions of DKK1, DKK2, sclerostin, and sFRP-1 but lower expression of osteogenic microRNA and β-catenin." (PMID 37569816, 2023).
ischemic heart disease (2 papers, 2016 to 2024). "Due to the complicated nature of the in vivo environment, further in vivo studies will be conducted to confirm the cardioprotective effects of Sfrp1 on therapy of ischemic heart disease." (PMID 27048460, 2016).
keratoconus (2 papers, 2013 to 2016). A degenerative, structural disorder of the eye, characterized by a cone-shaped protrusion of the cornea. "Albeit, recent studies have shown that matrix metalloproteinases MMP1 and 9, AZGP1, SFRP1, IGKC and cell adhesion molecules ICAM-1 and VCAM-1 to be specifically regulated in keratoconus, indicating their probable exclusive role in keratoconus." (PMID 27493978, 2016).
kidney cancer (2 papers, 2014 to 2022). Primary or metastatic malignant neoplasm involving the kidney. "From this analysis 4 genes (FBN2, PCDH8, BNC1 and SFRP1) stand out as either particularly strong epigenetic biomarkers of kidney cancer or as significant predictors of patient outcome." (PMID 24454902, 2014).
leiomyoma (2 papers, 2023 to 2024). A well-circumscribed benign smooth muscle neoplasm characterized by the presence of spindle cells with cigar-shaped nuclei, interlacing fascicles, and a whorled pattern. "Expression of SFRP1 was downregulated in cellular leiomyoma and upregulated in usual leiomyoma." (PMID 37466765, 2024). "Others have also reported overexpression of WIF1 and other WNT-protein inhibitors such as SFRP1, FBXW11, NKD1, and SFPR4 in leiomyomas." (PMID 36835153, 2023). "In one study, SFRP1 was significantly upregulated in leiomyomas relative to normal adjacent myometrium while other Wnt inhibitors such as APC, DKK1, and DKK3 were significantly downregulated." (PMID 37466765, 2024).
liver cancer (2 papers, 2020 to 2023). An epithelial or non-epithelial malignant neoplasm that arises from the liver. "Relevant studies show that P16, RASSF1A, GSTP1, APC, p15 and SFRP1 genes are significantly hypermethylation in HBV positive liver cancer." (PMID 38304027, 2023). "Our data demonstrated that β-catenin mutant pediatric liver cancers are accompanied by a suppression of the WNT antagonist SFRP1, which promotes malignant tumor cell characteristics." (PMID 32189106, 2020). "Our findings indicate that the epigenetic suppression of SFRP1 represents an alternative mechanism for enhancing WNT/β-catenin signaling in the development of pediatric liver cancer, particularly in children diagnosed at older ages." (PMID 32189106, 2020). "To evaluate the utility of SFRP1 as a biomarker in pediatric liver cancer, we determined the gene expression level and DNA methylation status of SFRP1 in 45 pediatric liver tumor patient samples." (PMID 32189106, 2020). "In conclusion, we delineated an important role for the epigenetic silencing of SFRP1 in pediatric liver cancer cell lines and patient samples." (PMID 32189106, 2020). "Notably, in our pediatric liver cancer cohort, we detected a reduced SFRP1 gene expression in around 62% (28/45) of cases." (PMID 32189106, 2020). "Moreover, recent studies proposed a microRNA-dependent inhibition of SFRP1 in different cancer entities, which may also occur in pediatric liver cancer." (PMID 32189106, 2020). "Since SFRP1 suppression contributes to elevated WNT/β-catenin signaling, which is a known characteristic of HB and HCC, we were highly interested in the functional role of SFRP1 in pediatric liver cancers." (PMID 32189106, 2020). "Although in several tumor entities, SFRP1 expression or methylation was proposed as a prognostic biomarker, this was not the case for our cohort of pediatric liver cancers." (PMID 32189106, 2020). "However, the role of the WNT inhibitory factor secreted frizzled-related protein 1 (SFRP1) has not been addressed in pediatric liver cancer so far." (PMID 32189106, 2020). "Thus, a restoration of the SFRP1 expression through epigenetic drugs or the natural compound flavonoid epigallocatechin-3-gallate (EGCG), as it was shown in our recent study, could be a new therapeutic option for β-catenin mutant pediatric liver cancers." (PMID 32189106, 2020).
Myocardial fibrosis (2 papers, 2021). "In this study, we show that the sFRP-1/Wnt/β-catenin axis plays a role in the prevention of myocardial fibrosis and improvement of myocardial remodeling in the context of ARNI treatment." (PMID 34539406, 2021). "In general, Sfrp1 overexpression can effectively reduce the degree of myocardial fibrosis in the early stage of AMI, inhibit cardiomyocyte apoptosis, and thus improve post-AMI injury healing and cardiac function in aged mice." (PMID 33468190, 2021). "Importantly, we show that ARNI improves myocardial fibrosis, prevents myocardial remodeling, and inhibits the Wnt/β-catenin signaling pathway via the upregulation of sFRP-1 in the context of MI." (PMID 34539406, 2021). "Sfrp1 might be used as a small molecule gene therapy drug to improve heart function, reduce the degree of myocardial fibrosis, inhibit cardiomyocyte apoptosis and reduce AMI injury in aged mice by inhibiting the Wnt/β-catenin pathway, thereby effectively protecting aged hearts from AMI injury." (PMID 33468190, 2021). "After Sfrp1 overexpression, Col-1 expression was significantly downregulated compared to the corresponding MI group, suggesting that abnormal deposition of myocardial ECM (Col-1) is improved by Sfrp1 overexpression and that myocardial fibrosis is reduced." (PMID 33468190, 2021). "Here, we aimed to assess the efficacy of ARNI for alleviating myocardial fibrosis after MI and hypothesized that ARNI alleviates myocardial fibrosis by inhibiting the Wnt/β-catenin signaling pathway and overexpressing sFRP-1, an inhibitor of the Wnt/β-catenin signaling pathway." (PMID 34539406, 2021). "The results showed that Sfrp1 was successfully overexpressed in the myocardium of aged mice and remarkably reduced Wnt/β-catenin pathway activity in aged mice after AMI, effectively reducing the degree of myocardial fibrosis, inhibiting cardiomyocyte apoptosis, and improving cardiac function." (PMID 33468190, 2021).
myopia (2 papers, 2013 to 2023). "Moreover, the SFRP-1 gene was identified to be related to myopia in 2 large-scale genome-wide association studies, implicating its clinical relevance to myopia formation." (PMID 37644183, 2023). "Furthermore, genetic knockdown of the cochlin gene and pharmacological blockade of SFRP1 abrogates the reduced choroidal blood perfusion and prevents myopia progression in the FDM model." (PMID 37644183, 2023). "SFRP-1 might then activate nonconical Wnt Ca2+/CaMKII signaling and cause dysfunction in choroidal vascular endothelial cells, leading to reduced choroidal blood perfusion and myopia formation." (PMID 37644183, 2023). "Due to the difficulty in obtaining ocular posterior pole tissues from subjects with nonpathologic myopia, the expression patterns of cochlin and SFRP-1, the 2 actionable targets identified in this study, have not been validated in clinical samples." (PMID 37644183, 2023). "The axis consisting of different signaling molecules, including cochlin, SFRP1, and CaMKII, and the corresponding tissue cell types, such as retinal photoreceptors, RPE cells, and choroidal vascular endothelial cells, was newly identified and proven to be responsible for myopia pathogenesis." (PMID 37644183, 2023). "Moreover, targeting cochlin and SFRP1 on this axis prevented myopia progression in the FDM model by improving choroidal circulation, indicating the potential of these molecules as interventional targets for myopia." (PMID 37644183, 2023). "Furthermore, genetic knockdown of Coch gene expression and pharmacological blockade of SFRP-1 impeded the progression of nonpathologic myopia by augmenting choroidal blood perfusion in the FDM model, implicating the potential of these 2 molecules as myopia intervention targets." (PMID 37644183, 2023). "Moreover, despite several lines of evidence in this study supporting the role of the cochlin/SFRP-1/CaMKII axis in the pathogenesis of nonpathologic myopia, the possibility that their overexpression may be the consequence of AL elongation cannot be excluded." (PMID 37644183, 2023). "A proteomics study using Guinea Pig ocular posterior pole tissues identifies a novel axis composed of cochlin in the retina, SFRP1 in the RPE, and CaMKII in choroidal vascular endothelial cells responsible for non-pathologic myopia." (PMID 37644183, 2023).
Oral Squamous Cell Carcinoma (2 papers, 2020 to 2022). "Qiao and co-workers also demonstrated miR-27a-3p promotes epithelial–mesenchymal transition (EMT) occurrence by targeting Sfrp1 and activating the Wnt/β-catenin signalling pathway in oral squamous cell carcinoma." (PMID 32484208, 2020).
pituitary adenomas (2 papers, 2015 to 2019). "A review of 13 whole genome approaches in pituitary tumors with the goal of identifying Wnt family inhibitors showed that expression of WF1, SFRP2, FRZB, SFRP4, DKK2, and SOSTDC1 genes is decreased in pituitary adenomas compared to normal pituitary tissue, while that of SFRP1 and SFRP4 is increased." (PMID 25834571, 2015). "Secreted frizzled-related protein 1(sFRP1) and Wnt inhibitory factor 1(WIF-1) genes were found to be less expressed in invasive non-functioning pituitary adenomas." (PMID 30733705, 2019).
postmenopausal osteoporosis (2 papers, 2021 to 2025). Metabolic disorder associated with fractures of the femoral neck, vertebrae, and distal forearm. "Resveratrol ameliorates bone loss in OVX mice by upregulating osteogenesis-associated genes and reducing SFRP1 levels, potentially useful for treating postmenopausal osteoporosis." (PMID 40243497, 2025). "In Group 3 (postmenopausal osteoporosis, without fractures), the REL of: GSK3B and SFRP1 positively correlated with TH BMD (R=0.560, p = 0.046 and R=0.703, p = 0.007) and TH T-score (R=0.560, p = 0.046 and R=0.703, p = 0.007), respectively." (PMID 33357212, 2021).
psoriasis (2 papers, 2012 to 2025). An autoimmune condition characterized by red, well-delineated plaques with silvery scales that are usually on the extensor surfaces and scalp. "In psoriasis, a skin condition typified by hyperproliferative epidermis, SFRP1 expression was also significantly lower than control normal skin." (PMID 40319033, 2025). "However, the repression of Wnt3 as well as the dysregulation of SFRP1 and SFRP2 are only found in invasive cutaneous SCC, but not psoriasis." (PMID 22384081, 2012).
skin squamous cell carcinoma (2 papers, 2022 to 2025). A carcinoma arising from the squamous cells of the epidermis. "SFRP1 expression was decreased in squamous cell skin cancer (SCC) compared to normal control skin." (PMID 40319033, 2025).
squamous cell carcinoma (2 papers, 2016 to 2024). A carcinoma arising from squamous epithelial cells. "We investigated SFRP1 expression between HDAC inhibitor-resistant cell lines and non-resistant cell lines for adenocarcinoma and squamous cell carcinoma and found different levels of SFRP1 expression." (PMID 27534621, 2016).
systemic sclerosis (2 papers, 2015 to 2021). A chronic disorder, possibly autoimmune, marked by excessive production of collagen which results in hardening and thickening of body tissues. "In systemic sclerosis (SSc), scholars have found that microRNA-27a-3p targeting sFRP-1, a negative regulator of Wnt signaling, in dermal fibroblasts mediates fibrosis regression." (PMID 34140947, 2021).
acute myeloid leukaemia (1 paper, 2020). "Secretion of extracellular SFRP1 establishes crosstalk with adhesion molecules in acute myeloid leukaemia cells and contributes to drug resistance." (PMID 32764696, 2020).
Apert syndrome (1 paper, 2011). Apert syndrome (AS) is a frequent form of acrocephalosyndactyly, a group of inherited congenital malformation disorders, characterized by craniosynostosis, midface hypoplasia, and finger and toe anomalies and/or syndactyly. "Also, a recent microarray study comparing osteoblast expression from wild-type and Apert syndrome fetuses identified concurrent WNT2 and SFRP1 upregulation in the tissues derived from syndromic craniosynostosis cases." (PMID 22028906, 2011).
atherosclerosis (1 paper, 2022). A disease characterized by the build-up of fatty material and calcium deposition in the arterial wall resulting in partial or complete occlusion of the arterial lumen. "Based on the results above, we think miR-1a-3p participates in the process of atherosclerosis by targeting the sFRP1/Wnt/PCP-JNK axis." (PMID 35464772, 2022). "Since sFRP1 is a secreted protein and macrophage activation is only a driving factor of atherosclerosis, sFRP1 can act on other adjacent cells, such as endothelial cells and vascular smooth muscle cells; thus, research on this topic is ongoing." (PMID 35464772, 2022). "In conclusion, these results indicate that EPA ameliorates the inflammatory response and oxidative stress in atherosclerosis via the miR-1a-3p/sFRP1/Wnt/PCP-JNK axis." (PMID 35464772, 2022). "Since the Wnt/PCP-JNK pathway is closely associated with lipid metabolism, inflammation, and cell proliferation and sFRP1 is known to regulate Wnt/PCP-JNK in cardiac myoblasts, we explored whether miR-1a-3p regulated the inflammation induced by atherosclerosis via sFRP1/Wnt/PCP-JNK signaling." (PMID 35464772, 2022). "Although there has been research on sFRP1 and the Wnt/PCP-JNK pathway in cardiomyocytes during cardiac injury, research on sFRP1 and Wnt/PCP-JNK in macrophages during atherosclerosis is novel." (PMID 35464772, 2022).